MFAP5 (microfibril associated protein 5)
Diseases named in the same sentence as MFAP5 in open-access papers (continued):
Sharing a sentence is not in itself a finding about the gene and the disease.
tumor (continued). "Overall, our findings emphasize that MFAP5 + fibroblasts and myeloid cells exhibit complicated intercellular interactions that aggravate tumor malignancy." (PMID 37344903, 2023). "In contrast, there were few C1QC + macrophages around the MFAP5 + fibroblasts in normal tissues, suggesting that crosstalk between these cells mainly occurred in tumor tissues." (PMID 37344903, 2023). "We demonstrated that tumor-resident MFAP5 + fibroblasts and myeloid cells (particularly C1QC + macrophages) were positively correlated in both spatial transcriptomics and bulk RNA-seq public cohorts." (PMID 37344903, 2023). "In TCGA database, elevated mRNA expression of overall MFAP5 in tumor tissues indicated both poorer overall survival (OS) and relapse-free survival (RFS) of PDAC patients." (PMID 37156839, 2023). "Considering the crucial role of MFAP5 + fibroblasts in tumor-driven signaling pathways in the TME, we performed intercellular interaction analysis to understand the potential pro-tumorigenic mechanisms." (PMID 37344903, 2023). "Subsequently, we applied the online tool TIMER to investigate the pan-cancer differential expression of MFAP5 between tumor and normal tissues." (PMID 37344903, 2023). "Given that MFAP5 inhibition downregulated PD-L1 expression on tumor cells in vivo, we further demonstrated downregulation of PD-L1 on tumor cells when cocultured with MFAP5_KD CAFs in vitro." (PMID 37156839, 2023). "By reviewing the MFAP5‐IHC staining of iCCA specimens, we noticed that the positive staining of MFAP5 was abundant in iCCA tissues, especially in the tumour stroma." (PMID 36855786, 2023). "Increased MFAP5 expression has been reported to stimulate cancer cell motility and invasion and predicted poor survival, and MFAP5 in vivo silencing reduced tumor progression." (PMID 35657798, 2022). "Patients with FIGO stage I or II cancer had significantly lower MFAP5 expression in the tumor than patients with advanced stage (FIGO III or IV) cancer (pairwise testing)." (PMID 36555638, 2022). "MFAP5 expression in the tumor stroma was as follows: seven samples (6.48%) had strong expression (score 3), 20 samples (18.52%)—moderate expression (score 2), and 81 samples (75%)—weak expression (score 1)." (PMID 36555638, 2022). "There was also a significant difference in MFAP5 staining between serous tumors vs. tumor adjacent normal tissue (NAT) (exact Fisher test, p = 0.003)." (PMID 36555638, 2022). ", who assessed preliminary IHC images, we decided to evaluate the MFAP5 expression within two compartments separately: first in cancer cells, then in the tumor stroma." (PMID 36555638, 2022). "Components of the CAF secretome, such as microfibrillar-associated protein 5 (MFAP5), have a similar pro-tumour effect." (PMID 36313650, 2022). "Similar dependence concerned MFAP5 expression and tumor grade: patients with well-differentiated (G1) tumors had significantly lower MFAP5 expression than patients with moderately or poorly differentiated (G2 & G3) tumors (pairwise testing)." (PMID 36555638, 2022). "Of note, MFAP5 activated Notch 1 signaling in certain tumors, promoting tumor invasion and migration." (PMID 34865619, 2021). "A series experiments demonstrated that MFAP5 promote tumor migration and invasion of HNSCC both in vitro and in vivo through AKT pathway." (PMID 32047565, 2020). "MFAP5 promotes tumor progression and bone metastasis in several cancers, and miR-200b-3p negatively regulates MFAP5 expression; finally, AC005154.6 interacts with miRNA-200b-3p." (PMID 32457800, 2020). "For the first time, we linked hypoxia, MFAP5 and metastasis into one process and proved that MFAP5 played an important role in hypoxia induced tumor progress in HNSCC." (PMID 32047565, 2020). "Combining with the fact that MFAP5 enhanced the expression of snail, we assumed that MFAP5 promotes tumor metastasis by activate the EMT program." (PMID 32047565, 2020).
tumor (continued). "We observed that the tumor growth rate of MFAP5-silenced groups was markedly slower than that of the control groups for both RBE and SSP-25 cell lines." (PMID 31775892, 2019). "The results showed that MFAP5 mRNA expression level was significantly higher in ICC tissues than in para-tumor tissues." (PMID 31775892, 2019). "The mode and mechanism of the suppression of tumor aggressiveness by MFAP5 depletion are potentially important." (PMID 31775892, 2019). "Our findings also revealed an important mechanism underlying amplified Notch activation in ICC that is mediated by MFAP5 in the tumor microenvironment." (PMID 31775892, 2019). "This study contributes to the understanding of the molecular mechanism by which MFAP5 overexpression in BLBC promotes tumor progression." (PMID 30899449, 2019). "TNNC1 was an effector protein of MFAP5 in stomata, which promoted cell motility and invasion potential via tumor-stroma crosstalk and subsequently affected clinical outcomes." (PMID 27713166, 2017). "Interaction with MFAP5+ fibroblasts in tumor tissue and facilitating tumor progression." (PMID 40191203, 2025). "In cancer, MFAP5 was found to function in tumor growth, metastasis, and angiogenesis." (PMID 39759103, 2024). "CAFs located at the invasive tumor front (CAFs-F), characterized by higher expression of the fibroblast activation marker SMA, were found to secrete elevated levels of microfibril-associated protein 5 (MFAP5) in comparison to NFs and the superficial tumor (CAFs-S)." (PMID 39744628, 2024). "Finally, due to challenges in obtaining CAFs from fresh tumor samples, additional experiments both in vivo and in vitro are required to determine MFAP5 expression profiles in tumor cells and CAFs." (PMID 39524442, 2024). "Significant associations were found between MFAP5 expressions with tumor grade and stage but not lymph node or distant metastasis stages." (PMID 39524442, 2024). "We found that MFAP5 was present not only in tumor tissues but also in fibroblasts from non-tumor tissues, with comparable expression levels between normal and tumor tissues, suggesting a unique role for MFAP5 or cluster 6 within both microenvironments." (PMID 39524442, 2024). "The ELISA showed that the medium of CAFs had higher levels of MFAP5 than that of tumour cells." (PMID 36855786, 2023). "Notably, MFAP5 knockdown was in synergy with PD-L1 based immunotherapy and gemcitabine treatment to inhibit tumor growth potently." (PMID 37156839, 2023). "This suggests the existence of tumor-specific factors, such as cell-to-cell interactions, that could significantly impact the properties of MFAP5 + fibroblasts, thus prompting its pro-tumor role." (PMID 37344903, 2023). "Thus, overall expression of MFAP5 in tumor tissues was correlated with a poor prognosis in patients with PDAC." (PMID 37156839, 2023). "Notably, MFAP5 deficiency remodels the matrix via inhibiting CAF activation and increases infiltration of cytotoxic CD8+ T cells to tumor niches." (PMID 37156839, 2023). "However, patients with higher infiltration of MFAP5 + fibroblasts in tumor regions experienced worse prognosis than those with lower infiltration." (PMID 37344903, 2023). "We observed that MFAP5 + fibroblasts-derived microfibrils could adhere to the C1QC + macrophages in tumor border stromal region rather in tumor invasive margin." (PMID 37344903, 2023). "Moreover, to confirm that CAFs act on tumour cells via ligand MFAP5, we analyzed the single‐cell RNA‐seq dataset GSE138709 by using the NicheNET method." (PMID 36855786, 2023). "Mechanistically, MFAP5 deficiency in CAFs downregulates HAS2 and CXCL10 via MFAP5/RCN2/ERK/STAT1 axis, leading to angiogenesis, hyaluronic acid (HA) and collagens deposition reduction, cytotoxic T cells infiltration, and tumor cells apoptosis." (PMID 37156839, 2023).
tumor (continued). "In vivo assays, MFAP5 promoted tumor progression by increasing angiogenesis, tumor growth, invasion, and metastasis and MFAP5 blockade using monoclonal antibodies was able to inhibit fibrosis and enhance chemosensitivity in mouse models, generating tumor suppression." (PMID 37168385, 2023). "Additionally, overexpression of MFAP5 protein was also observed in PDAC tumor tissue compared with paired para-cancerous tissues in western blotting." (PMID 37156839, 2023). "EGF signaling was uniquely upregulated in tumor-localized MFAP5 + fibroblasts." (PMID 37344903, 2023). "We extrapolated that MFAP5 + fibroblasts could drive tumor development by signal coordination with FAP + fibroblasts." (PMID 37344903, 2023). "Notably, a higher risk of recurrence was close to statistical significance for patients with higher MFAP5 expression in the tumor (p = 0.062)." (PMID 36555638, 2022). "It remains to be clarified how MFAP5 affects tumor vasculature." (PMID 36555638, 2022). "One month after removal of the LUAD, expression of MET, PLTP and MFAP5 all decreased, which could be attributed to the radical tumor removal." (PMID 36544145, 2022). "Notably, in our study, we observed a trend toward worse OS when we merged samples with stronger MFAP5 expression in both the stromal and epithelial compartment of the tumor, and compared them against all other samples." (PMID 36555638, 2022). "Our findings not only suggested that hypoxia environment could stimulate tumor cell to secret MFAP5 but also proved that MFAP5 promotes EMT program in HNSCC." (PMID 32047565, 2020). "Our research demonstrated for the first time that this lack oxygen environment could stimulate tumor cell to secret MFAP5." (PMID 32047565, 2020). "In consistent with our previous study, MFAP5 has a high expression inside HNSCC tumor tissue." (PMID 32047565, 2020). "In the present study, we found that hypoxia condition could induce MFAP5 expression by HNSCC cells which indicated that tumor cells are also an important resource of MFAP5." (PMID 32047565, 2020). "However, current studies of MFAP5 are majorly focus on its impact for tumor cells and the critical role of tumor microenvironment is often overlooked." (PMID 32047565, 2020). "Furthermore, similar results were found in xenograft mouse tumor sections, suggesting that MFAP5 promoted EMT in vivo." (PMID 30899449, 2019). "The tumor weight was significantly lower in the MFAP5-silenced groups than in the control groups." (PMID 31775892, 2019). "The expression level of MFAP5 differed statistically between tumor and para-tumor tissues." (PMID 31775892, 2019). "Therefore, the inappropriate activation of EGFR in tumor-localized MFAP5 + fibroblasts could partly account for its malignant behavior." (PMID 37344903, 2023). "Additionally, in vivo blockade of CXCL10 with AMG487 could partially reverse the pro-tumor effect from MFAP5 overexpression in CAFs and synergize with anti-PD-L1 antibody to enhance the immunotherapeutic effect." (PMID 37156839, 2023). "We speculated that TME-specific factors, such as bioactive molecules, complicated intercellular interactions, and stimuli, contribute to the alteration of the biological properties of tumor-resident MFAP5 + fibroblasts confers these cells with a tumor-promoting tendency." (PMID 37344903, 2023). "While this phenotype might be associated with tumor immune escape, we hypothesized that the change from CSF1 to IL-34 could be important during the MFAP5 + fibroblasts mediated promotion of tumor malignancy through the driving of the immune evasive phenotype of C1QC + macrophages." (PMID 37344903, 2023). "Additionally, we observed that along with stronger desmoplastic reaction in the tumor, there was a significantly greater percentage of samples with stronger MFAP5 expression, either in cancer cells or in the tumor stroma (exact Fisher test, p = 0.035 and p < 0.001, respectively)." (PMID 36555638, 2022).
tumor (continued). "In addition, in vivo assay observes that overexpression of MFAP5 can promote tumor lung metastasis." (PMID 32047565, 2020). "Moreover, MFAP5 is believed to be secreted mainly by tumor stroma cells." (PMID 32047565, 2020). "We found that in tumor tissues, FAP+ and MFAP5+ fibroblasts have most communication pathways with TAMs, suggesting that FAP+ and MFAP5+ fibroblasts play an important regulatory role within the TME." (PMID 40438108, 2025). "Analysis of the communication patterns of CAFs and TAMs also showed a coordinated tumor-promoting signaling communication model between FAP+ and MFAP5+ fibroblasts." (PMID 40438108, 2025). "We found that CAF subtypes 0 (BTG1+ CAF), 2 (CFD+ CAF), and 4 (IGFBP7+ CAF) were more abundant in the tumor than the normal, while CAF subcluster 1 (OGN+ CAF), 3 (C1R+ CAF), 5 (MFAP5+ CAF), and 6 (SFRP4+ CAF) were more abundant in the normal than the tumor." (PMID 38686196, 2024). "Through in-depth analyses, we also identified for the first time that the close localization of MFAP5 + fibroblasts and tumor-associated macrophages, especially C1QC + macrophages (previously identified macrophages with pro-inflammatory role), could facilitate the tumor invasive phenotype." (PMID 37344903, 2023). "We observed that MFAP5 + fibroblasts mainly infiltrated fibroblast areas that were close to M2-phenotype macrophages (marked by CD68 and CD163) but opposite to anti-tumor T cells or B cells." (PMID 37344903, 2023). "We observed that MFAP5 + and FAP + fibroblasts had the highest number of communications with other stromal and immune cells in the tumor, indicating their active biological properties." (PMID 37344903, 2023). "Our results provide comprehensive information regarding the physiological functions of MFAP5 + fibroblasts, with emphasis on their cell-to-cell crosstalk with C1QC + macrophages and other tumor-infiltrating myeloid cells." (PMID 37344903, 2023). "Outgoing communication pattern analysis also suggested a coordinated pro-tumor signaling pathway between FAP + and MFAP5 + fibroblasts, which have long been verified as a tumor-driven stromal population." (PMID 37344903, 2023). "For example, among 10 markers that are localized in the tumor stroma according to IHC images, 4 genes (MFAP2, MFAP5, PDGFRA, CDH11) are specifically represented in “Fibroblasts”, while the remaining markers are expressed in both cell types." (PMID 36263012, 2022). "Combining tumor-normal and inter-tumor analyses, we identified overexpressed targets including PDGFRB, FGFR4, ERBB2/3, CDK6 kinases and MFAP5, HMCN1, and Hsp proteins in HCC, many of which showed low frequencies of genomic and/or transcriptomic aberrations." (PMID 35433463, 2022). "We found that MFAP5 mRNA expression was related to the FIGO stage and histological grade of the tumor." (PMID 36555638, 2022). "The expression level of MFAP5 and HIF-1α was remarkably correlated in same tumor species (r=0.493, P<0.01)." (PMID 32047565, 2020). "IHC analysis showed that positive staining of the MFAP5 protein was enriched in ICC tissues, but was rarely observed in para-tumor and normal tissues." (PMID 31775892, 2019). "Chitosan nanoparticles have shown effectiveness in targeting CAF-derived tumorigenic factor, MFAP5, in vivo, and chitosan nanoparticles labeled with RGD peptides localize to the tumor vasculature and exert anti-angiogenic effects." (PMID 26751490, 2016). "Furthermore, the mIHC assay confirmed the co-localization of MFAP5 + fibroblasts and C1QC + macrophages within the tumor regions." (PMID 37344903, 2023). "However, in tumor tissues, C1QC + macrophages receive CSF signaling from both MFAP5 + and FABP5 + fibroblasts, suggesting an immunomodulatory role in CRC." (PMID 37344903, 2023). "Results showed that the high value of regulatory potential between MFAP5 and some of its top predicted NOTCH1/WNT pathway target genes (CCND1, HES1, MYC, RBPJ, NOTCH1, CCN3, CTNNB1 and SOX17) in inferring signaling paths in tumour tissues." (PMID 36855786, 2023).
tumor (continued). "Furthermore, in xenograft models, the enhanced tumor proliferation (Ki67) and decreased angiogenesis (CD31) due to MFAP5 overexpression in CAFs was also partially reverted by application of AMG487, along with increased Granzyme B+CD8+T cells infiltration." (PMID 37156839, 2023). "We found that more than 60% of patients with complete or partial response to chemotherapy had weak MFAP5 expression in cancer cells, whereas patients with tumor progression or no change in tumor size had stronger MFAP5 expression." (PMID 36555638, 2022). "As a key promotor of EMT progression, this result reminded us that MFAP5 might promote the expression of EMT phenotypic protein by activate snail, thus leading to tumor metastasis." (PMID 32047565, 2020). "Furthermore, we demonstrated that MFAP5 promoted the tumorigenesis and metastasis of BLBC in vivo by developing tumor xenograft and axillary lymph nodes, lung metastasis models." (PMID 30899449, 2019). "The results of this study suggest that MFAP5 may activate the TGF-β and Notch signaling pathways to promote EMT, leading to an aggressive phenotype and tumor progression to metastasis." (PMID 30899449, 2019). "The Spint2 transcript was homogenously expressed in the tumor epithelium, but not in the stroma, as identified by the mCAF-specific transcript Mfap5." (PMID 30514914, 2018). "We observed that MFAP5 + fibroblasts were the main senders that could release complement C3 to interact with the receptors ITGAM/ITGB2, ITGAX/ITGB2, and C3AR1 of C1QC + macrophages in tumor tissues, thus activating the complement system." (PMID 37344903, 2023). "But MFAP5 was not an active ligand in tumour‐adjacent tissues." (PMID 36855786, 2023). "Intercellular interaction analysis suggested that MFAP5 + fibroblasts could reciprocally communicate with C1QC + macrophages and other myeloid cells to remodel unfavorable conditions via MIF/CD74, IL34/CSF1R, and other tumor-promoting signaling pathways." (PMID 37344903, 2023). "In addition, tumor-specific MFAP5 + fibroblasts could also secrete FN1 and TGF-β to interact with certain receptors of myeloid cells to promote tumor progression." (PMID 37344903, 2023). "Therefore, MFAP5 was involved in CAF activation, tumor proliferation and metastasis in vitro." (PMID 37156839, 2023). "Hence, we hypothesized that aberrant signal communication between MFAP5 + fibroblasts and C1QC + macrophages promotes the tumor-invasive phenotype to a certain extent." (PMID 37344903, 2023). "In tumor samples gene expression analysis showed no significant variation between WT and heterozygous KIT mutated tumors, with a high inner variability in ANXA8, FBN1, GALNTL4, MFAP5 and RABEP1 expression, which was partly reduced by separating exon 9 and exon 11 mutated tumors." (PMID 23593401, 2013). "Although no studies of COL5A1 and MFAP5 in ESCC have been reported, these two genes are involved in tumor metastasis in other types of tumors." (PMID 38136265, 2023). "Conversely, 26 genes, including mediators of epithelial–mesenchymal transition (i.e., COL6A1/A2, COL16A1, MFAP5, MMP11), were co-expressed in tumor tissue but not in NAU." (PMID 35626146, 2022). "One month after surgery, the three proteins, PLTP, MET and MFAP5, showed a decreasing trend, and when compared to patients without LUAD, the significance was no longer found, possibly indicating tumor removal." (PMID 36544145, 2022). "To validate these findings, we evaluated the expression level of MFAP5 in a cohort of 24 pairs of ICC and para-tumor (non-cancerous) tissues." (PMID 31775892, 2019). "Conversely, some genes (VSIG4, MFAP5, THY1, TSHZ2) showed little to no expression in tumor cells." (PMID 40954493, 2025).